MMP1 (matrix metallopeptidase 1)
Diseases named in the same sentence as MMP1 in open-access papers (continued):
Sharing a sentence is not in itself a finding about the gene and the disease.
cancer (continued). "TCGA data analysis showed that high NMUR2 levels are characteristic of cancers with low differentiation and increased invasiveness, as represented by decreased CDH1 expression and increased MMP1 expression." (PMID 34493299, 2021). "Although PTHLH, MMP1 and MMP10 were mainly up-regulated in the 21 cancer types, the rest of the members GATM and ARHGEF26, were primarily down-regulated with a few exceptions." (PMID 34301206, 2021). "ICAM1, MMP1, and MMP3 are the well-known biomarkers participating in regulating cancer cell migration and invasion." (PMID 34544905, 2021). "Matrix metalloproteinase 1 and 3 (MMP1 and MMP3), which are in the matrix metalloproteinase family, are also overexpressed in many cancers." (PMID 33564686, 2021). "EMMPRIN induces a metastatic phenotype by triggering the production of matrix metalloproteinase proteins (MMPs) such as MMP1 and MMP2, and vascular endothelial growth factor (VEGF) in cancer cells and the surrounding stromal cells." (PMID 34565336, 2021). "In general, the mRNA expression levels of ADAM12, MMP1, SERPINE1, PLOD3, and P4HA3 were correlated with immune infiltration score and macrophages and dendritic cells (DCs) in most types of cancer." (PMID 34121340, 2021). "The ECM‐receptor interaction gene set was further analyzed for correlation with ADAM12, MMP1, SERPINE1, PLOD3, and P4HA3 in the 29 cancer types." (PMID 34121340, 2021). "The most predominant ECM regulators, ADAM12, MMP1, SERPINE1, PLOD3, and P4HA3, have been classified as a five‐gene signature that produces a broad effect over 29 types of cancer." (PMID 34121340, 2021). "As a result, CXCL10, IGF1, MMP3, MMP1, ICAM1, and IL-13 levels were markedly up-regulated within NPC samples relative to the non-carcinoma samples (P < 0.05)." (PMID 34544905, 2021). "On the other hand, the inhibition of JNK pathway repressed the c-Jun phosphorylation and NOX4 expression, followed by the inhibition of ROS production, MMP-1 and MMP-9 expression, and invasion ability in OA-treated cancer cells." (PMID 32641980, 2020). "According to previous studies, VEFG-1, ICAM-1, TGF-β2, MMP-1, and MMP-9 are key genes involved in the regulation of cancer cell metastasis and invasion." (PMID 32210104, 2020). "Our results showed that treatment of cancer cells with celecoxib and miR-101-3p inhibitor reduces COX-2 and MMP1 protein expression as well transmigration of BC cells through the brain endothelium compared to cells treated with miR-101-3p inhibitor alone." (PMID 32645833, 2020). "Genistein also displays down-regulation of all MMP genes (MMP-1,−2,−3,−7,−9,−11,−14,−15,−16) along with up-regulation of TIMP-1 level while TIMP-2 level is being suppressed in MDA-MB-231 and MCF-7 cancer cell lines." (PMID 33520928, 2020). "Despite the general notion that collagenases (MMP1, MMP8 and MMP13) are key players in cancer biology, relatively little is known about collagenases in PDAC." (PMID 32325664, 2020). "Although MMP-1 is consistently shown to be overexpressed in PDAC patients compared to healthy controls, its effects on cancer progression are inconsistent." (PMID 32325664, 2020). "Upon examination of VE-cadherin, ephrin A2, VEGFR2, laminin 5γ2, MMP1, MMP2, MMP9 and MMP14 by the human cancer cells, we made the surprise finding that of the genes investigated, VE-cadherin (CDH5) was the most highly expressed." (PMID 32246008, 2020). "The autocrine and paracrine actions of identified pain and metastasis genes (e.g., MMP1 and PAR1), as well as communication via exosomes, are potential therapeutic targets for stopping cancer and alleviating pain." (PMID 32895418, 2020). "This grouping in cluster 2 features high expression of gene cluster B genes (MMP3, MMP10, MMP13, MMP1, and MMP12) in a pattern that is relatively unique among cancer types." (PMID 31200666, 2019). "Several of the genes, including MMP1, MMP2, TIMP1 and HIF1A, are known cancer genes and facilitate stromal invasion." (PMID 31748560, 2019).
cancer (continued). "In line with this, ETV1 overexpression can lead to increased transcription of the matrix metalloproteinase 1 (MMP1) and MMP7 genes, which both are important for cancer cell invasion." (PMID 31160676, 2019). "For improving the understanding of SEMA6A-derived migration pathway, we also determined the mRNA expression levels of PLAU, MMP1 and MMP9 using RT-qPCR, because these genes were indicated to be reduced by HMOX1 and to induce migration in cancer cells." (PMID 31527696, 2019). "Collagenases, MMP1 and MMP13, were significantly altered in 11 cancer types and 12 cancer types, respectively (p = 5E-05 to 1E-77)." (PMID 31200666, 2019). "The reduced expression of MMP1 and inhibition of migration on ST08 treatment indicate that this compound can modulate metastasis by inhibiting migration of cancer cells." (PMID 31638975, 2019). "MMP1, MMP9, MMP10, MMP11, and MMP13 were almost universally upregulated across all cancers, with significant (p < 0.05) fold change (FC > 2) in ten of fifteen cancers." (PMID 31200666, 2019). "Although MMP1 and MMP2 are well-known regulators of cardiac ECM components, MMP11 has been observed in endometrium and human carcinomas." (PMID 31513610, 2019). "Several zinc‐containing matrix‐degrading endopeptidases (MMP‐1, MMP‐2, MMP‐3), which are known regulators of tissue remodeling in aging and cancer, were also included in the selected list of metformin targets." (PMID 29740925, 2018). "MMP1, a member of the MMP family, can degrade interstitial collagen types I, II, and III, clearing a path for cancer cells to invade matrix barriers and migrate through tissue stroma." (PMID 30627228, 2018). "Top five up-regulated genes in malignant tumours were COL11A1, SFRP2, LCN2, COL2A1 and H19, while top up-regulated genes in benign tumours were MMP3, MMP1, AREG, PTHLH and SFRP2." (PMID 30517191, 2018). "MMP1 is a proteolytic enzyme which degrades ECM, and its upregulated expression status has been detected among several kinds of malignant tumors." (PMID 29207651, 2017). "Our recent work demonstrates that DR5 suppression promotes cancer cell invasion and metastasis through caspase-8/TRAF2-mediated activation of ERK and JNK signaling and MMP1 elevation." (PMID 28482915, 2017). "Compared to normal colon, we observed robust MMP1 mRNA over-expression in 16 of the 18 cancer specimens (89%), but we were unable to identify a quantitative relationship between CHRM3 and MMP1 expression levels." (PMID 28416748, 2017). "All marker levels were found significantly different between healthy controls and cancer subjects (Mann-Whitney U test, P = 0.002 for EGF, sCD26, CAL, MMP-9, CEA and CYFRA 21.1; P = 0.018 for MMP-1 and MMP-7)." (PMID 28117344, 2017). "The candidate genes including BGN, MMP1, LGALS1, SERPINB5, and TM4SF4 probably correlated with cancer development and the EMT program mediated by the integrated pathway of TGFβ/Snail with TNFα/NFκB." (PMID 28687755, 2017). "MMP1 and MMP14 have been reported to induce cancer cell invasion, and MMP14 is further recognized in the activation of MMP2 and MMP9." (PMID 26981862, 2016). "MMP1 is a matrix metallopeptidase 1 protein involved in proteolysis of ECM and thus in cancer metastasis; HGF is known to induce cell scattering." (PMID 27982133, 2016). "Overexpression of MMP1, MMP2, MMP3, MMP7, MMP9, and MMP13 correlates with worse outcomes in cancer patients." (PMID 27908290, 2016). "Significantly, candidate genes MMP1, CDC45, and CAT were also, respectively, enriched in the pathway in cancer, cell cycle, and methane metabolism." (PMID 27034707, 2016).
cancer (continued). "The overexpression of many MMP family members, such as MMP1, MMP2, MMP7, MMP9, and MMP11 has been found to be involved in cancer progression; therefore, the development of MMP inhibitors has become an effective strategy in clinical cancer therapies." (PMID 26084486, 2015). "While HIF-1α is known to regulate proteolytic enzymes such as uPAR, cathepsins, MMP-1, MMP-2, MMP-9 in many cancer types, HIF-2α has directly been involved in membrane bound MT1-MMP in von Hippel-Lindau renal cell carcinoma." (PMID 26305551, 2015). "Matrix metalloproteinases (MMPs), especially MMP1 and MMP9, are critical enzymes responsible for the degradation of the basement membrane (BM) and extracellular matrix (ECM), thereby contributing to cancer invasion and metastasis." (PMID 26337460, 2015). "Certain previous studies have shown that EGF stimulates the expression of MMP1 and MMP9 in several cancers." (PMID 24765152, 2014). "Our data show that MMP-1 can regulate the levels of TGF-α in culture supernatants of the MDA-MB-231-BR and -BR3 cells, which in turns affects activity of EGFR in the cancer cells." (PMID 23217186, 2012). "In mucosal tissue from inflamed UC, collagen synthesis, pro-MMP-1, TIMP-1, pro-MMP-9 and IL-1β were significantly increased (p<0.03, all comparisons) compared to cancer control tissues." (PMID 23300643, 2012). "Taken all together, these results suggested that galectin-3 increased the expression of both PAR-1 and MMP-1, and that the increased MMP-1 expression activated PAR-1 signaling, which in turn, facilitated cancer cell invasion." (PMID 21966428, 2011). "73.7% of the cancer patients showed higher expression levels of galectin-3 and 70% of them showed higher PAR-1 and MMP-1 levels in their malignant tissues than in their normal counterparts." (PMID 21966428, 2011). "By inhibiting plasmin, TFPI-2 effectively decreases the activation of MMP-1, MMP-3 and MMP-9 and reduces the invasive potential of several cancer cell lines." (PMID 21062455, 2010). "From a clinical point of view, IL1RN, MAL and TGM3 were not clearly identified as potential HNSCC markers, while few data have been published concerning the implication of FN1, KRT, MMP1, PLAU and SPARC in this type of cancer." (PMID 19835631, 2009). "Colocalization of MMP-1 and MMP-3 with destruction of ECM in the invasive front of cancer tissue suggests a direct role in cancer invasion." (PMID 17919326, 2007). "The MMP-1/CXCR4 axis modulates activated fibroblast behavior in both RA and cancer." (PMID 40567613, 2025). "Considering that MMP1 plays a role in the migration, invasion, and metastasis of cancer cells, the anticancer effect of EGCG may be partly attributed to its suppression of MMP1 expression." (PMID 40427522, 2025). "Furthermore, we found that MMP1/CCL5/ ALDH1A3, which have been identified as cancer‐promoting genes, were the downstream targets of the CPS1/PC‐PLC/DAG/PKC axis." (PMID 39387452, 2024). "STAT5A signaling, CSPG4, MMP-1, MMP-3, MMP-8, MMP-9, and LUM are all involved in cancer cell migration, invasion, and metastasis, while PKM supports the growth and survival of cancer cells by favoring aerobic glycolysis." (PMID 39201614, 2024). "In LA3IK-treated samples, a significant downregulation was observed among genes central in cancer-related inflammation and epithelial-mesenchymal transition (EMT), exemplified by the reduced expression of IL1B, CXCL-8, matrix metalloproteinase 1 (MMP-1), and Zeb-1." (PMID 38272230, 2024). "Several studies have demonstrated that MMP1, MMP2, MMP9, MMP13 and MMP19 in some cancer tissues such as NSCLC or gastric cancer are all raised, and these MMP members can degrade basement membrane and open the channel for cancer’s invasion and metastasis." (PMID 38560562, 2024).
cancer (continued). "In fact, it has been reported that in cancer cells, the GCX functions as a mechanosensory organ that senses interstitial flow, and affects the expression of matrix metalloproteinase‐1 (MMP‐1), MMP‐2, CD44, and α3 integrin which regulate cell motility and metastasis induced by interstitial flow." (PMID 39300946, 2024). "When elevated levels of phosphorylated STAT3 in NFs were eliminated upon TPCA-1 treatment, in our case, MMP1 was not upregulated and the invasiveness of cancer cells was not promoted." (PMID 38320998, 2024). "Althrough elevated expression of MMP1 was observed in both cancer and stromal cells, it is not clear which type of cells it mainly comes from." (PMID 38320998, 2024). "Similarly, MMP1 and MMP7 contribute to the breakdown of the ECM, allowing cancer cells to penetrate tissue barriers and spread." (PMID 38707175, 2024). "MMP1 (matrix metalloproteinase 1) is a member of the MMP family, which play a role in the degradation of extracellular matrix and regulate the biological behavior of cancer cells." (PMID 37484321, 2023). "According on the results of observations and statistical analysis, it was found that the number of cells expressing vimentin, MMP1, and PDGF in ductal type cancers was different from the lobular type cases that underwent local recurrence after mastectomy and adjuvant chemotherapy." (PMID 38046195, 2023). "The discovery in this study that galectin-3 increases the secretion of Cathepsin-B, MMP-1, and MMP-13 by cancer cells suggests that increasing the secretion of proteases is probably one of the mechanisms behind galectin-3-mediated cancer promotion reported in many previous studies." (PMID 37055381, 2023). "MMP-1 and MMP-13 are primarily responsible for ECM degradation in cancer progression." (PMID 37055381, 2023). "After CRISPR/Cas9-mediated disruption of IE8, cancer cells showed a switch in the MMP expression signature, specifically downregulating the pro-invasive MMP1 gene and upregulating the antitumorigenic MMP8 gene, resulting in reduced invasive ability and collagen degradation." (PMID 38017545, 2023). "MMP1, MMP3, and MMP12 were up-regulated in both inflammation and cancer." (PMID 35850748, 2022). "INHBA, MMP1, and SERPINE1 comprised a protein-protein interacting (PPI) network according to STRING network analysis, and these genes were significantly increased in cancer tissues or MSI cancer tissues." (PMID 35909892, 2022). "Therefore, we investigated the correlation between MMP1 expression and TMB/MSI in 32 types cancers via SangerBox." (PMID 35948625, 2022). "Thus, epithelial mesenchymal transition (EMT) marker proteins (SNAIL, fibronectin, E-cadherin, MMP-1, MMP-9 and vimentin) as well as cancer cell migration and invasiveness processes were analyzed in the presence of E2." (PMID 36419896, 2022). "It was confirmed that purinergic antiplatelet agents can be involved in cancer metastasis by inducing the expression of MMP1, which is involved in cell motility, by increasing the secretion of SERPINE1 in cancer cells while decreasing cancer cell proliferation." (PMID 36076991, 2022). "As interstitial collagenase, abnormal expression of MMP1 was seen in the development of cancer." (PMID 35444805, 2022). "MMP-1 was the first collagenase described and it is expressed by fibroblasts, endothelial cells, or keratinocytes, while an increased MMP-1 expression has been reported in various inflammatory diseases and cancers." (PMID 36713871, 2022). "Additionally, MMP1 and MMP2 can enhance cellular growth and migration in cancer and wound-healing models." (PMID 35328555, 2022). "Although there have been several reports on serum MMP1 in the context of exploring biomarkers for human cancers, according to our knowledge, no previous study has evaluated serum MMP1 as a prognostic marker in CC patients after RT." (PMID 34727105, 2021).
cancer (continued). "Collectively, these results suggest tumoral mRNA expression of MMP1, MMP9, COL1A1 and LAIR1 significantly impacts survival of cancer patients, and therefore led to the hypothesis that MMP generated collagen I fragments might activate LAIR-1." (PMID 34691040, 2021). "MMP-1 is part of the family of collagenases and is able to degrade interstitial collagens I, II, and III, resulting in denatured collagen or gelatin, and its upregulated expression status has been detected among several kinds of malignant tumors." (PMID 34445715, 2021). "Collagenase activity assays were performed to evaluate the activities of MMPs (MMP-1, -2 and -9) that were secreted from GCB-treated Huh7 cells and could degrade the extracellular matrix around the cancer cells." (PMID 33567682, 2021). "The data on primary cells suggested that the cells from MMP1 patient could be responsive to IPZ and that IPZ could also enhance the sensitivity of cancer cells to cisplatin administration." (PMID 32659970, 2020). "In addition, three common signature genes in the pathways concerning cancer were endothelin receptor B (EDNRB), hedgehog-interacting protein (HHIP), and MMP1." (PMID 33046043, 2020). "A panel of MMPs was analyzed in serum from PC patients—specifically, MMP-1, MMP-3, MMP-7, MMP-9, MMP-10, and MMP-12 were higher in cancer patients compared with healthy donors, showing good diagnostic accuracy, of which MMP-7 and MMP-12 achieved perfect discrimination." (PMID 30678058, 2019). "LDD-1819 treatment reduced the expression of MMP-1 and MMP-2 in the cancer cells." (PMID 31489353, 2019). "The LuCSC-holoclones were EpCAM+ (morphologically epithelial), and negative for classical EMT genes AXL, CD10, Zeb1 and MMP1 that are involved in motility and invasive behavior of mesenchymal cancer cells." (PMID 31069016, 2019). "However, it appears that MMPs are important enzymes involved in local attack and metastatic PTC cancer, being reported in several studies related to different members of the MMP family, including MMP-1, MMP-2, MMP-7, MMP-9, MMP-10, MMP-13, MMP-14 and MMP-15." (PMID 30509240, 2018). "Fifteen members of cancer pathways, including FOS, TGFα, FZD8, MMP1, laminin subunit gamma 2, PTGS2, laminin subunit beta 3, ITGA2, laminin subunit alpha 3, VEGFC, WNT2B, heat shock protein 90 beta family member 1, WNT5B, FGF5 and WNT3A, were up-regulated in the MC group." (PMID 30482199, 2018). "Interestingly, high-throughput analysis of Cancer Genome Atlas data identified distinct targets, including Fatty acid synthase FASN and Matrix Metallopeptidase 1 MMP1 as novel, promising combination therapy partners." (PMID 30283446, 2018). "Direct pharmacologic comparative studies in relevant cancer cell lines between vorapaxar, atopaxar, PZ-128 and other PAR1-derived pepducins using a set of proteases agonists such as thrombin, MMP-1, MMP-13 and elastase could address this question." (PMID 30065181, 2018). "Furthermore, AREG affected downstream molecules like BIRC5, CCNA2, CCNB2, TOP2A, MMP9, MMP1, CXCR4, have roles in development and progression of various types of cancers." (PMID 30517191, 2018). "Among the 70 cancer-associated proteins evaluated, MMP members MMP-1, -7 and -9 were considered, although they were not included in the final diagnostic rule." (PMID 29207990, 2017). "C/EBP β also induces MMP1/3 expression via the p38 mitogen-activated protein kinase (MAPK) pathway to mediate tumor necrosis factors (TNF)-α-induced cancer cell migration, contributing to the regulation of cancer metastasis." (PMID 27011164, 2016).